NEIL3 (nei like DNA glycosylase 3)
Diseases named in the same sentence as NEIL3 in open-access papers (continued):
Sharing a sentence is not in itself a finding about the gene and the disease.
glioblastoma (7 papers, 2017 to 2025). The most malignant astrocytic tumor (WHO grade IV). "Klattenhoff found that the loss of NEIL3 enhanced sensitivity to ATR inhibitors in glioblastoma cells." (PMID 33921035, 2021). "In addition, another study demonstrated that loss of NEIL3 enhances sensitivity to ATR inhibitors in glioblastoma cells." (PMID 34591415, 2021). "Research has revealed the impact of DNA repair genes, especially NEIL3, on glioblastoma progression and resistance." (PMID 40033009, 2025). "Our results further suggest that NEIL3 status should routinely be assessed in several cancer types, including glioblastoma, that likely provide a novel therapeutic opportunity to target tumors that carry altered levels of NEIL3." (PMID 29348879, 2017). "This study suggests that for patients with NEIL3-deficient tumors, the combination of ATR inhibitors with olaparib may be useful in treating glioblastoma patients, which has significant clinical implications." (PMID 36497204, 2022). "NEIL3 is overexpressed in several cancers including glioblastoma multiforme (GBM) and significantly reduces survival rates." (PMID 29348879, 2017). "Upregulated NEIL3 expression was significantly positively correlated with the stromal score of THCA and negatively correlated with that of GBM (glioblastoma multiforme) and SARC (sarcoma)." (PMID 36612106, 2022).
Fanconi anemia (6 papers, 2014 to 2025). Fanconi anemia (FA) is a hereditary DNA repair disorder characterized by progressive pancytopenia with bone marrow failure, variable congenital malformations and predisposition to develop hematological or solid tumors. "In ICL repair, Zfp212, the mouse homolog of ZNF212, appears to act upstream Neil3 and Fanconi anemia (FA) pathways in the same way as Traip does." (PMID 36594163, 2023). "Subsequently, TARIP has been shown to ubiquitylate the replicative CMG (CDC45/MCM2–7/GINS) helicase, thereby regulating the NEIL3 pathway and Fanconi anemia pathway in the DNA interstrand crosslink repair process." (PMID 34349117, 2021). "In addition, an epistatic analysis of Zfp212, the mouse homolog of human ZNF212, in mouse embryonic stem cells (mESCs), shows that it appears to act upstream of both the Neil3 and Fanconi anemia (FA) pathways of ICLs repair." (PMID 36594163, 2023). "TONSL knockdown significantly reduced the expression of FANCD1 and XRCC2, both key players in the Fanconi anemia and homologous recombination repair pathways, while DDB2 and NEIL3 showed no statistically changes." (PMID 39944694, 2025).
prion disease (6 papers, 2016 to 2025). A transmissible disease that is caused by a protein that is able to induce abnormal folding of normal cellular proteins, leading to characteristic spongiform brain changes, which are associated with neuronal loss without an inflammatory response. "The DNA glycosylase function of NEIL3 in the brain is associated with hippocampus-dependent memory and neurogenesis after stroke and in prion diseases." (PMID 40033009, 2025). "To elucidate the impact of oxidative DNA damage-induced neurogenesis on prion disease we applied the experimental prion disease model on Neil3-deficient mice." (PMID 27886261, 2016). "Expression levels of NeuN, a marker for mature neurons, dropped significantly more in Neil3-deficient brain than wild type during prion disease, probably due to severe neuronal loss, indicating that the neurogenic capacity is impaired in Neil3 KO." (PMID 27886261, 2016). "Our observations of a significantly shortened clinical phase of prion disease in mice compromised in different BER enzyme activities, such as Mutyh and Ogg112 and here in Neil3 deficient mice suggest that during clinical prion disease, DNA glycosylase activities provide neuroprotection." (PMID 27886261, 2016). "NEIL3 protects against prion disease exacerbation due to oxidative DNA damage during neurodevelopment." (PMID 40033009, 2025). "Neuronal nuclei (NeuN), a marker for mature neurons declined during prion disease and more pronounced in the Neil3−/− group." (PMID 27886261, 2016). "In this study, we demonstrate that Neil3 protects the brain during the clinical phase of prion disease." (PMID 27886261, 2016). "In order to evaluate the activation state of microglia at onset and end-stage prion disease in wild-type and Neil3 Ko mice we compared expression levels of microglial markers Cd68, Cd86 and inflammation markers TNFα and Il1ß at both time-points." (PMID 27886261, 2016). "Our data suggest that neurogenesis induced by Neil3 repair of oxidative DNA damage protects against prion disease during the clinical phase." (PMID 27886261, 2016). "Thus, given its role in proliferation of NSCs and neurogenesis, the impact of NEIL3 on prion disease has been investigated." (PMID 34884729, 2021). "Therefore, in order to broaden our understanding of hippocampal neurogenesis during neurodegeneration, we report a study of prion disease in mice with genetic knockout (KO) of Neil3." (PMID 27886261, 2016). "Additionally, prion disease is a severe neurodegenerative disease, and NEIL3 seemed to protect brain tissue from oxidative damage by inducing neurogenesis, which could prevent prion disease in the clinical stage." (PMID 36497204, 2022). "Contrarily, neurogenesis induced by the enzyme Neil3, which eliminates oxidative DNA base damage, protects mice against scrapie strain RML prion disease during the clinical phase." (PMID 38004683, 2023). "It thus appears that the Neil3 DNA glycosylase is not important for removing oxidative DNA base lesions genome-wide during prion disease." (PMID 27886261, 2016). "Despite the fact that DNA repair capacities appears to be gradually overwhelmed during prion disease, neither this nor the lack of Neil3 elicit any compensatory increase in expression levels of other DNA glycosylases with overlapping substrate specificities (i.e. Neil1 and Neil2)." (PMID 27886261, 2016). "Thus, repair of NEIL3-dependent oxidative lesions does not likely affect the clinical outcome of the disease, raising the possibility that NEIL3 may exert a function beyond canonical BER in prion disease." (PMID 34884729, 2021).
glioma (5 papers, 2018 to 2022). A benign or malignant brain and spinal cord tumor that arises from glial cells (astrocytes, oligodendrocytes, ependymal cells). "Previous studies have shown that NEIL3 overexpression exhibited an association with genomic changes and low survival in some types of human carcinomas, such as glioma." (PMID 35387222, 2022). "In the present study, we identified a circRNA derived from NEIL3, hsa_circ_0001460, named circNEIL3, by analysing the expression profiles of circRNAs in glioma tissues." (PMID 35031058, 2022). "In this study, we first demonstrated that circNEIL3, which is derived from NEIL3, is frequently upregulated in glioma tissues, and its expression increases with increasing glioma grade." (PMID 35031058, 2022). "After calculating the hazard ratio and confidence interval, we observed that 8 hub genes in hub network 1 were related to the poor prognosis of gliomas, including PBK, KIF2C, CENPE, KIF14, MND1, FAM83D, NEIL3, and CDKN3." (PMID 35387222, 2022).
lung adenocarcinoma (5 papers, 2016 to 2025). A carcinoma that arises from the lung and is characterized by the presence of malignant glandular epithelial cells. "The transcription factor, MAZ, increases NEIL3 expression and inhibits DNA damage in lung adenocarcinoma cells, thereby promoting cisplatin resistance in the lung adenocarcinoma cells." (PMID 40761744, 2025). "The transcription factor, MYC associated zinc finger protein (MAZ), functions as an upstream regulator of NEIL3 to directly promote its transcription and this induces cisplatin resistance in lung adenocarcinoma." (PMID 40761744, 2025). "Of note, NEIL3 was overexpressed in different types of cancers, including invasive breast carcinoma, pancreatic adenocarcinoma, and lung adenocarcinoma." (PMID 36233194, 2022).
melanoma (5 papers, 2009 to 2023). A malignant, usually aggressive tumor composed of atypical, neoplastic melanocytes. "Responders to pembrolizumab and ipilimumab had higher NEIL3 mutation rates in non-small-cell lung cancer and melanoma, respectively." (PMID 36612106, 2022). "Elevated expression of NEIL3 occurs in many human cancer cell types and tissues and is associated with primary malignant melanomas and metastasis." (PMID 32631357, 2020). "NEIL3 has also been shown to be highly expressed in primary malignant melanomas associated with metastasis." (PMID 19426544, 2009). "NEIL3 was therefore suggested to be associated with the progression of primary melanoma to distant metastasis." (PMID 19426544, 2009). "However, in melanoma, responders to pembrolizumab and nivolumab had lower NEIL3 mutation rates, suggesting that different cancers require personalized customization with regard to immunotherapy." (PMID 36612106, 2022). "In a recent study, NEIL3 was shown to be overexpressed in primary melanomas giving rise to metastasis." (PMID 19426544, 2009). "The overexpression of NEIL3 is also related to metastasis and poor prognosis in melanoma patients." (PMID 36816967, 2023). "Likewise, the melanoma patient’s response to the first administration of nivolumab revealed a higher expression of NEIL3." (PMID 36612106, 2022). "NEIL3 has recently been shown to be highly expressed in melanomas." (PMID 19426544, 2009). "Although without statistical significance, our results suggested the possibility that ipilimumab may demonstrate greater efficacy in melanoma patients with a high non-silent mutation rate of NEIL3." (PMID 36612106, 2022). "Additionally, in our study, responsive melanoma patients treated with ipilimumab presented a higher non-silent mutation rate of NEIL3 than non-responsive patients." (PMID 36612106, 2022). "Moreover, NEIL3 is highly expressed in primary malignant melanomas, which may induce metastatic tumors." (PMID 33879165, 2021).
lung carcinoma (4 papers, 2022 to 2025). "Lower doses of lycopene improve the levels of NEIL1, NEIL2, and NEIL3 in cigarette smoke-induced A549 human lung cancer epithelial cells." (PMID 40761744, 2025). "Meanwhile, a higher NEIL3 mRNA expression level was also observed in lung cancer tissue." (PMID 35535347, 2022). "This study is aimed at exploring the role of NEIL3 in lung cancer." (PMID 35535347, 2022). "NEIL3 is upregulated in NSCLC tissues, suggesting that NEIL3 is involved in the occurrence and development of lung cancer." (PMID 40761744, 2025). "NEIL3 was upregulated in NSCLC tissues and cell lines, implying that it is involved in lung cancer initiation and progression." (PMID 35535347, 2022). "Lycopene masked lung cancer proliferation by suppressing oxidative stress as well as by elevating 8‐oxo guanine DNA glycosylase (OGG1), connexin‐43 (Cx43), and Nei‐like DNA glycosylases (NEIL1, NEIL2, and NEIL3) expression." (PMID 40661795, 2025). "Nei endonuclease VIII-like 3 (NEIL3) is widely involved in pathophysiological processes of the body; however, its role in lung cancer has not been conclusively determined." (PMID 35535347, 2022). "Unlike NEIL1 and NEIL2, NEIL3 functions as an oncogenic factor in lung cancer." (PMID 40761744, 2025).
myocardial infarction (4 papers, 2016 to 2023). Gross necrosis of the myocardium, as a result of interruption of the blood supply to the area, as in coronary thrombosis. "Recently, we showed that a genetic variant in the human DNA repair enzyme NEIL3 was associated with increased risk of myocardial infarction." (PMID 27328939, 2016). "Moreover, a nested case–control study revealed that genetic variation of NEIL3 rs12645561 SNP TT genotype was associated with an increased risk of myocardial infarction." (PMID 36497204, 2022). "However, in Neil3-/--deficient mice, there was a significantly increased risk of a myocardial rupture occurring after myocardial infarction due to dysregulated proliferation and differentiation of fibroblasts caused by Neil3-/- deficiency, resulting in increased early mortality." (PMID 36497204, 2022). "NEIL3 has also been reported to mediate the lipid metabolism and macrophage function in myocardial infarction." (PMID 36741311, 2023).
breast invasive carcinoma (3 papers, 2016 to 2022). "Rad51, NEIL3 and BLM, which were linked to invasive breast cancer and BRIP1 that was associated with IDC and LC, are the only genes to our knowledge that were previously linked to invasive breast carcinoma." (PMID 33662042, 2021). "NEIL3 is also overexpressed in breast invasive carcinoma and its upregulation positively correlates with the decrease in the survival of triple negative breast cancer (TNBC) patients." (PMID 33662042, 2021).
ischemic stroke (3 papers, 2009 to 2021). A stroke disorder caused by obstruction of blood flow to the brain, due to thrombotic (local blood clot formation) or embolic (due to a blood clot or other material traveling from another site) event. "Knockout of NEIL3 induces severe neuropathy, and NEIL3 knockout mice exhibited poor outcomes after ischemic stroke." (PMID 34563140, 2021). "Studies using the Neil3 knockout mice model that involve insults to the brain such as ischemic stroke would be central in revealing whether Neil3 has a role in the regeneration of damaged tissue." (PMID 19426544, 2009). "Hence, we speculated that hsa_circ_0001459 may exert its effect by regulating its host gene NEIL3 in ischemic stroke." (PMID 34563140, 2021).
lymph node metastasis (3 papers, 2021). "The TCGA dataset demonstrated that high NEIL3 was associated with a high T stage and Gleason score, and indicated a possibility of lymph node metastasis, but a good prognosis." (PMID 33921035, 2021). "All risk factors and NEIL3 expression levels were subjected in the univariate Cox regression analysis; of them, these were associated with OS: TNM stage, tumor size, lymph node metastasis, and NEIL3 expression (p < 0.001)." (PMID 33879165, 2021). "We found that a high mRNA level of NEIL3 was related to a higher Gleason score (P = 0.000) and T stage (P = 0.000) and indicated a higher possibility of lymph node metastasis (P = 0.006)." (PMID 34591415, 2021). "Statistical analyses showed that a high protein level of NEIL3 was related to a high Gleason score (P = 0.015 and 0.036, respectively) but not to PSA level, T stage, lymph node metastasis, or distant metastasis." (PMID 34591415, 2021).
non-small cell lung carcinoma (3 papers, 2022 to 2025). A group of at least three distinct histological types of lung cancer, including non-small cell squamous cell carcinoma, adenocarcinoma, and large cell carcinoma. "NEIL3 expression is upregulated in non-small-cell lung cancer (NSCLC)." (PMID 40761744, 2025).
pancreatic adenocarcinoma (3 papers, 2021 to 2022). "NEIL3 is increased in several tumors, such as pancreatic adenocarcinoma (PAAD), lung adenocarcinoma (LUAD), and lower-grade glioma (LGG), and it seems to be highly expressed in cells with proliferative potential." (PMID 36612106, 2022).
Anxiety (2 papers, 2022 to 2025). Intense feelings of nervousness, tension, or panic often arise in response to interpersonal stresses. "Notably, Neil3−/− mice exhibited impaired hippocampus-dependent learning and memory as tested in the Morris water maze task and reduced anxiety-like behavior in the elevated zero maze." (PMID 40035863, 2025).
clear cell renal cell carcinoma (2 papers, 2016 to 2023). "In addition, we divided 265 renal clear cell carcinoma samples from GSE73731 into two groups based on the median NEIL3 expression level." (PMID 36816967, 2023).
colorectal cancer (2 papers, 2022 to 2023). A primary or metastatic malignant neoplasm that affects the colon or rectum. "For example, circ-NEIL3, a TGFβ-repressive circular RNA, was identified as a potential biomarker for colorectal carcinoma liver metastasis." (PMID 37783059, 2023).
esophageal cancer (2 papers, 2022 to 2025). A primary or metastatic malignant neoplasm involving the esophagus. "ECA109 esophageal cancer cells were used to assess the impact of NEIL3 overexpression and TOP2A knockdown on proliferation, colony formation, migration, invasion, and apoptosis." (PMID 39910812, 2025).
lung squamous cell carcinoma (2 papers, 2016 to 2022). "NEIL3 expression was also positively related to cancer stage, such as adrenocortical carcinoma (ACC), kidney chromophobe (KICH), KIRC, kidney renal papillary cell carcinoma (KIRP), LIHC, LUAD, and lung squamous cell carcinoma (LUSC)." (PMID 36612106, 2022).
pancreatic ductal adenocarcinoma (2 papers, 2021 to 2025). An infiltrating adenocarcinoma that arises from the epithelial cells of the pancreas. "Specifically, the circ-NEIL3 regulatory mechanism promotes the multiplication of pancreatic ductal adenocarcinoma cells by means of A-to-I RNA editing." (PMID 39794701, 2025). "Circ-NEIL3 provides a novel marker for the diagnosis and prognosis of pancreatic ductal adenocarcinoma (PDAC) via miR-320-5p/AdAR1." (PMID 34905439, 2021).
stomach adenocarcinoma (2 papers, 2016 to 2022). "Notably, the high expression level of NEIL3 was significantly related to shorter DFI in most cancers, while it was the opposite in stomach adenocarcinoma (STAD)." (PMID 36612106, 2022).
age (1 paper, 2025). A temporal measurement of the time period elapsed since an identifiable point in the life cycle of an organism. "Given the importance of adult neurogenesis in cognitive function, targeting NEIL3 could offer therapeutic potential for addressing age-related hippocampal dysfunction and cognitive decline." (PMID 40035863, 2025).
Alzheimer disease (1 paper, 2025). A progressive, neurodegenerative disease characterized by loss of function and death of nerve cells in several areas of the brain leading to loss of cognitive function such as memory and language. "Interestingly, in a mouse model of Alzheimer’s disease, NEIL3 depletion impaired adult hippocampal neurogenesis and hippocampus-dependent working memory." (PMID 40035863, 2025).
anemia (1 paper, 2021). A reduction in the number of red blood cells, the amount of hemoglobin, and/or the volume of packed red blood cells. "Also in the signature were genes encoding the DNA glycosylase NEIL3, Fanconi Anemia factors (FANCD2, UBE2T), the ubiquitin protein ligase UBE3B, and two specialized DNA polymerases, POLM and POLQ, involved in the non-homologous end-joining (NHEJ) pathways of DSB repair." (PMID 34067180, 2021).
asthma (1 paper, 2021). "The asthma and aldosterone-regulated sodium reabsorption pathways were enriched in the low NEIL3 expression cohort." (PMID 33879165, 2021).
autoimmune disease (1 paper, 2020). "The association with autoimmune disease appears especially strong in the case of NEIL3." (PMID 32547565, 2020). "Importantly, the homozygous missense mutation found in the NEIL3 gene (D132V) in the consanguineous NEIL3 deficient patients is present in about 2% of healthy individuals from Middle Eastern descent, but whether this confers an increased risk to develop autoimmune disease remains to be studied." (PMID 32547565, 2020).
carotid atherosclerosis (1 paper, 2016). A thickening and loss of elasticity of the walls of carotid arteries that occur with formation of atherosclerotic plaques. "Herein, we report marked upregulation of NEIL3 expression in carotid atherosclerosis as compared to non-atherosclerotic vessels in two separate cohorts." (PMID 27328939, 2016).